NUPR1 (nuclear protein 1, transcriptional regulator)
Diseases named in the same sentence as NUPR1 in open-access papers (continued):
Sharing a sentence is not in itself a finding about the gene and the disease.
breast cancer (continued). "This was consistent with high protein levels of NUPR1 in TNBC cell lines (MDA-MB-231, MDA-MB-468, 4T1 and BT549 cells are TNBC cell lines; T47D and MCF-7 are ER positive breast cancer cell lines)." (PMID 41429768, 2025). "Conversely, in both breast cancer cell lines, O-desmethyltramadol consistently downregulated the expression of SLC16A1, CD22, NUPR1, ASNS, and DDIT3." (PMID 40362379, 2025). "In contrast, the expression levels of NUPR1 mRNA and ERBB2 protein in the luminal-A subtype-like MCF7 (labelled with a blue colored asterisk in the figure) breast cancer cells are low, as expected." (PMID 39991577, 2025). "Since the upregulation of NUPR1 correlates with poor clinical outcomes in ER+ and ERBB2 (HER2)-enriched breast cancer patients, we sought to further confirm the role of NUPR1 in the induction of estrogen independence in ER+ breast cancer cells." (PMID 39991577, 2025). "Studies have demonstrated that estrogen receptor-positive breast cancer cells, and TNBC cell lines and tissue have elevated levels of NUPR1." (PMID 38405101, 2024). "Here we identify that NUPR1, a tamoxifen (Tam)-induced transcriptional coregulator, is necessary for the maintenance of Tam resistance through physical interaction with ESR1 in breast cancers." (PMID 33542201, 2021). "Notably, the current study reveals a new role of Nuclear Protein 1 (NUPR1/P8/COM1) in regulating the expression of HDAC5, ERBB2 (and the survival reliance switch from estrogen to EGF) and BIRC5 (a well-known oncogene) in breast cancer cells." (PMID 39991577, 2025). "Thus, we examined possible relationships between the expression of NUPR1 and ERBB2 in breast cancer cells." (PMID 39991577, 2025). "Intriguingly, high NUPR1 expression levels also correlate with poor overall survival (despite not reaching statistical significance) and poor relapse-free survival in ERBB2-enriched breast cancer patients." (PMID 39991577, 2025). "Downregulation of NUPR1 by siRNA decreased the amount of both the ERBB2 mRNA transcripts and the ERBB2 proteins present in the ER+ ERBB2high MCF7-TamC3 and the ER- ERBB2high (ERBB2-enriched subtype-like) SK-BR-3 breast cancer cells." (PMID 39991577, 2025). "Functionally, up-regulated NUPR1 promoted Cr(VI)-induced transformation of BEAS-2B cells, consistent with previous reports that NUPR1 promoted the development and metastasis of lung, pancreatic, and breast cancers." (PMID 36497250, 2022). "Our data indicate that NUPR1 depletion in ESR1-positive breast cancer cells overcomes Tam resistance; however, we do not know the exact functional associations of this protein except for those with ESR1." (PMID 33542201, 2021). "Our current study reveals that Nupr1, independent of Sox2, is low in three types of carcinoma TRCs (melanoma, ovarian cancer and breast cancer) and is a negative regulator of TRC growth." (PMID 27089143, 2016). "Here we show that nuclear protein 1 (Nupr1), a protein independent of Sox2, is downregulated in TRCs of melanoma, ovarian cancer and breast cancer cultured in soft fibrin matrices." (PMID 27089143, 2016). "Notably, most breast cancer cell lines with ERBB2/HER2 amplification, including the ERBB2 (HER2)-enriched subtype-like SK-BR-3 (labelled with a red colored asterisk in the figure), exhibit high levels of NUPR1 mRNA expression." (PMID 39991577, 2025). "The qPCR and the western blot analysis results revealed that NUPR1 positively regulates the expression of the epigenetic regulator HDAC5, the anti-apoptotic molecule BIRC5, and the mitogenic receptor ERBB2 in MCF7-TamC3 and the ERBB2-enriched subtype like SK-BR-3 breast cancer cells." (PMID 39991577, 2025).
breast cancer (continued). "NUPR1 could also active autophagy and bind to the promoter regions of some autophagy-related genes, such as BECN1, GREB1, RAB31, PGR, CYP1B1, thereby regulating breast cancer metastasis and transcription." (PMID 37626099, 2023). "Additionally, neither the active forms of lysosomal proteases cathepsin D nor the MTOR pathway were significantly altered in this process, indicating that autolysosomal degradation upon NUPR1 depletion is independent of the MTOR pathway in TamR breast cancer cells." (PMID 33542201, 2021).
pancreatic cancer (35 papers, 2012 to 2025). "In a mouse model of pancreatic cancer with constitutively expressed oncogenic Kras(G12D), loss of Nupr1 protected from the development of pancreatic intraepithelial neoplasias (PanINs)." (PMID 27285315, 2016). "Studies in animal models have suggested that Nupr1 is a key factor in the development of lung and pancreatic cancers, with little known about the underlying molecular mechanisms." (PMID 27285315, 2016). "In aggregate, these results demonstrate that the FoxO3a-Skp2-p27Kip1 pathway, first defined by our in vitro mechanistic experiments in cultured pancreatic cancer cells, associates with the Nupr1−/− genotype in vivo giving rise to OIS with a concomitant impairment in PanIN development." (PMID 24902898, 2014). "We generated EGFP- and DsRed-expressing batches of the Smad4-mutated BxPC3 pancreatic cancer cell line and determined whether such cells would perform cannibalism after Nupr1-depletion and TGFβ treatment." (PMID 22821859, 2012). "Thus, this work is very relevant to the field as we demonstrated that the pancreatitis-induced protein Nupr1 acts in concert with the mutated Kras to facilitate the progression of pancreatic cancer, at least in part, through permissive effects for bypassing senescence." (PMID 24902898, 2014). "Finally, in order to establish the pivotal role of Nupr1 in the repression of HoCC in vivo, we investigated whether Nupr1-deficiency resulted in more cell-in-cells in pancreatic tumours developed by the Pdx1-creER; LSL-KRASG12D; INK4A/ARFfl/fl mice." (PMID 22821859, 2012). "This supports a potential role for LZX-2-73 in modulating stress-response pathways involving NUPR1 in pancreatic cancer cells." (PMID 41249113, 2025). "NUPR1 functions as an oncogene in different types of tumors, such as breast, thyroid, brain, and pancreatic cancer." (PMID 40707944, 2025). "At present, although related studies have reported that NUPR1 can inhibit ferroptosis by transcriptionally regulating the expression of LCN2 in pancreatic cancer, promoting the initiation and development of tumours." (PMID 40176685, 2025). "The activation of this pro-survival mechanism driven by NUPR1 was described for pancreatic cancer cells in response to metabolic stresses such as hypoxia and glucose starvation." (PMID 40707944, 2025). "NUPR1-driven LLPS was crucial for the creation of NUPR1-dependent stress granules (SGs) in pancreatic cancer cells since genetic or pharmacological inhibition by ZZW-115 of NUPR1 activity impeded SGs formation." (PMID 38360999, 2024). "Altogether these data suggest that a strong overexpression of NUPR1 is sufficient to promote the formation of the NUPR1-dependent SGs population in pancreatic cancer cells, and that its activity can be inhibited by pharmacological means." (PMID 38360999, 2024). "ZZW-115, a synthesized NUPR1 inhibitor, has been found to suppress xenograft pancreatic tumor growth by inducing mitochondrial metabolism rupture and necrosis." (PMID 37989855, 2023). "NUPR1 inhibitor ZZW-115 was proved to sensitize pancreatic cancer cells to genotoxic agents, including γ-irradiation." (PMID 36258210, 2022). "The inactivation of NUPR1 triggers ROS overproduction due to mitochondrial failure in pancreatic cancer." (PMID 36258210, 2022). "Our previous study also showed that the inactivation of NUPR1 induced mitochondrial dysfunction including Ca2+ outflow, decreased ATP levels, and ROS increase in pancreatic cancer cells." (PMID 34359572, 2021). "Remarkably, we and others have previously showed that genetic inactivation of the Nupr1 gene antagonizes the growth of pancreatic cancer as well as several other tumors." (PMID 31744261, 2019). "In several in vitro and in vivo models of pancreatic cancer, NUPR1 down-regulation inhibits the development and growth of this malignant tumor, highlighting the translational importance of this protein." (PMID 30451898, 2018).
pancreatic cancer (continued). "In this paper we studied the metabolism changes after NUPR1 downregulation in pancreatic cancer cells, which results in a significant decrease of OXPHOS activity with a concomitant lower ATP production which precedes the necrotic cell death." (PMID 30451898, 2018). "Pancreatic cancers developed in KRAS-induced carcinomas and NUPR1-deficient mice exhibited a higher expression of stemness markers (ALDH1, SOX2, Oct-4) compared to tumors originated in NUPR1-WT mice." (PMID 29156578, 2017). "In this study, it was shown also that NUPR1 protected pancreatic cancer cells from apoptosis through a pathway dependent on transcription factor Relb and immediate early response 3 (IER3)." (PMID 29156578, 2017). "Nupr1 is induced by a variety of stressors and the induction of Nupr1 is required for the development of lung and pancreatic cancers in animal models." (PMID 27285315, 2016). "Nupr1 is a chromatin protein, which cooperates with KrasG12D to induce PanIN formation and pancreatic cancer development in mice, though the molecular mechanisms underlying this effect remain to be fully characterized." (PMID 26617245, 2015). "Complementary knockdown experiments using 2 specific Nupr1 siRNAs to transfect pancreatic cancer cells (MiaPaCa2) decreased Dnmt1 mRNA levels (3.8 fold ± 0.7; p < 0.01), without affecting either Dnmt3a or Dnmt3b expression." (PMID 26617245, 2015). "NUPR1 normally functions as a stress response gene in the pancreas, but it has been shown to contribute to metastasis, anti-apoptotic activity and pancreatic cancer development." (PMID 26191083, 2015). "Congruently, we find that the specific silencing of Nupr1 in pancreatic cancer cells increases the levels of the cyclin-dependent kinase (Cdk) inhibitor p27Kip1." (PMID 24902898, 2014). "To extend our in vivo results, we next explored the role of Nupr1 as a modifier of the effects of KrasG12D in cultured human pancreatic cancer cells." (PMID 24902898, 2014). "We observed that Nupr1 is overexpressed in several pancreatic tumor cells such as MiaPaCa2, Panc1, CaPan2 and BxPC-3 cells." (PMID 24902898, 2014). "More importantly, both of these cellular and molecular changes are recapitulated by the results of mechanistic experiments using RNAi-based inactivation of Nupr1 in human pancreatic cancer cell models." (PMID 24902898, 2014). "Consistent with the observations of cannibal cells in human pancreatic tumours, Nupr1-depleted Panc-1 cells displayed enhanced ectopic CD68 expression compared to controls." (PMID 22821859, 2012). "Thus, as KrasG12D activation induced NUPR1 overexpression and it played a critical role in the formation of SGs in pancreatic cancer cells, we aimed at analyzing the effect of SGs inhibition in 9805 i-Kras cells, upon ZZW-115-treatment or by NUPR1 siRNA." (PMID 38360999, 2024). "Histone methyltransferase Dot1L might inhibit pancreatic cancer cell apoptosis by targeting NUPR1, and overexpressed NUPR1 also inhibited pancreatic cancer cell apoptosis." (PMID 37626099, 2023). "The expression of NUPR1 is augmented in most pancreatic cancer patients." (PMID 36468653, 2023). "NUPR1 has the activity of promoting the division of pancreatic cancer cell lines." (PMID 36468653, 2023). "The expression of NUPR1 was determined to be upregulated in acute pancreatitis and, at even higher levels in pancreatic adenocarcinoma, NUPR1 can also interact with mut-KRas signaling in pancreatic cancer and other cells." (PMID 35883598, 2022). "NUPR1 may be a critical transcription factor which is induced in response to the cellular stress and could be a therapeutic target in pancreatic cancer progression." (PMID 35883598, 2022). "Moreover, nuclear protein 1 (NUPR1)-dependent regulation of NGAL expression inhibits ferroptosis in pancreatic cancer." (PMID 34830212, 2021).
pancreatic cancer (continued). "Altogether, these data enable us to describe a model in which inactivation of NUPR1 in pancreatic cancer cells results in an ER stress that induces a mitochondrial malfunction, a deficient ATP production and, as consequence, the cell death mediated by a programmed necrosis." (PMID 30451898, 2018). "Congruent with this line of research, in this work, we demonstrate that the chromatin binding protein, Nupr1, is a key molecule responsible for the crosstalk between genetic and epigenetic mechanisms that, by acting in concert, facilitate the progression of pancreatic cancer." (PMID 26617245, 2015). "Furthermore, Nupr1 expression controls pancreatic cancer cell migration, invasion and adhesion, three processes required for metastasis through CDC42, a major regulator of cytoskeleton organization." (PMID 24205110, 2013). "Finally, the genetic inactivation of Nupr1-enhanced cell cannibalism in KrasG12D INK4anull murine pancreatic tumours, indicating that Nupr1 expression antagonizes cell cannibalism in vivo within the primary tumour." (PMID 22821859, 2012). "Strikingly, a fraction of Nupr1-depleted cells appeared to cannibalize their siblings upon TGFβ treatment, giving rise to homotypic cell-in-cell bodies, consistent with the observations of Nupr1-negative cannibal cells in human pancreatic tumours." (PMID 22821859, 2012). "Therefore, to address whether NUPR1 was also actively involved in SGs formation in pancreatic cancer cells, we inactivated NUPR1 by using a specific siRNA or its pharmacological inhibitor ZZW-115." (PMID 38360999, 2024). "In addition, it was also demonstrated that NUPR1 overexpression is necessary in the liver for an optimal response to a non-essential aminoacids-deficient diet and in pancreatic cancer cells to a starved culture media." (PMID 30451898, 2018). "While investigating the pathways that lead to drug resistance, the transcriptional regulator NUPR1 (also known as anti-apoptotic protein p8 or Candidate of Metastasis-1) was identified as being involved in the acquisition of gemcitabine resistance by pancreatic cancer cells." (PMID 26191083, 2015). "Thus, these experimental manipulations in cultured human pancreatic cancer cells recapitulate the results obtained in genetically engineered mice and, together, demonstrate that normal levels of Nupr1 expression are necessary for both bypassing OIS and modulating neoplastic cell growth." (PMID 24902898, 2014). "Pharmacologically, inhibiting NUPR1 by ZZW-115 increases the mitochondrial and cellular ROS production in pancreatic cancer cells and induces cancer cell death." (PMID 39991577, 2025). "The NUPR1 inhibitor ZZW-115 downregulates TFAM, affecting the antioxidant system and promoting ferroptosis in pancreatic cancer cells." (PMID 38802795, 2024). "To further support these observations, we induced SGs formation in pancreatic cancer cells obtained from Pdx1-cre;LSL-KrasG12D/INK4a/Arf’fl/fl/NUPR1+/+ or Pdx1-cre;LSL-KrasG12D/INK4a/Arf’fl/fl/NUPR1-/- mice." (PMID 38360999, 2024). "NUPR1 binds to PARP1 and inhibits PARP1 activity in pancreatic cancer cells, with the NUPR1 inhibitor ZZW-115 abolishing the protective effect of NUPR1, inducing strong hyperPARylation and cell death by mitochondrial dysfunction." (PMID 35869257, 2022). "Similarly, our latest research also showed that the NUPR1 inhibitor ZZW-115 can inhibit TFAM expression, cause mitochondrial dysfunction, and produce more ROS production, thereby inducing ferroptosis in a variety of cancer cells such as pancreatic cancer cells and liver cancer cells." (PMID 34359572, 2021). "We measured the OCR in pancreatic cancer cells with Nupr1 siRNA-mediated knockdown or knockout by CRISPR-Cas9, as well as in pancreatic acini obtained from Nupr1-KO and WT mice." (PMID 30451898, 2018). "NUPR1 protected the pancreatic cancer cells from apoptosis by a RelB-mediated non-canonical NF-κβ pathway which interacted with immediate early response 3 (IRE3) protein." (PMID 35883598, 2022).
pancreatic cancer (continued). "We used specific siRNAs to test whether Nupr1 and MSL1 partners are involved in pancreatic cancer cell survival after DNA damage induced by cisplatin treatments." (PMID 24205110, 2013). "The upregulation of NUPR1 by ICG-001 may explain why ICG-001 plus gemcitabine did not increase overall lifespan in an in vivo pancreatic cancer cell xenograft model." (PMID 26191083, 2015). "The NUPR1 inhibitor ZZW-115 could block stress granule (SG) formation, induce apoptosis, and reduce pancreatic intraepithelial neoplasia development in KrasG12D-driven tumors, highlighting its potential as a therapeutic strategy for pancreatic cancer and other cancers." (PMID 41429768, 2025). "Indeed, knockdown of NUPR1 triggers the expression of lipid detoxification genes such as aldo-keto reductase family 1 member C1 (AKR1C1) in keratinocytes and pancreatic cancer cells but does not affect NRF2 expression or nuclear translocation." (PMID 34359572, 2021).